NOS2 (nitric oxide synthase 2)
Diseases named in the same sentence as NOS2 in open-access papers (continued):
Sharing a sentence is not in itself a finding about the gene and the disease.
tumor (continued). "Moreover, stimulation with mouse-derived recombinant SPP1 protein induced the expression of pro-tumor genes (such as Arg1, Slc2a1, and Nos2) in MDSCs while repressing the expression of anti-tumor genes (such as Il1b, Tnfa, and Il12b)." (PMID 39066845, 2024). "The M1 type metabolizes arginine via NOS2 to produce NO for anti-tumor activities." (PMID 39191486, 2024). "Given that elevated NOS2/COX2 tumor expression is a strong predictor of poor survival among ER– patients and patients with TNBC, we postulated that elevated expression of these enzymes might limit clinical outcome in conjunction with radiation treatment." (PMID 38912586, 2024). "The double-positive F4/80 + NOS2 + TAMs were more abundant in both the peritumoral stroma (0.67 ± 0.04 vs 0.98 ± 0.08, P = 0.029) and intratumoral regions (0.46 ± 0.06 vs 0.65 ± 0.02, P = 0.049) of PyMTSB2−/− tumor compared to those of PyMTWT tumors." (PMID 38956496, 2024). "NOS2 was significantly higher in the tumor satellite regions when compared with the tumor core." (PMID 39356141, 2024). "And we found a potential therapeutic targeting CAFs: hydrogen treatment could reduce Nos2 expression level on CAFs, further abating downstream pro‐tumor biomarkers." (PMID 38757665, 2024). "In contrast to ARG1, NOS2 in macrophages is pro-inflammatory and tumor suppressive." (PMID 38422022, 2024). "In the context of tumor environment, spermidine either intrinsically or in a paracrine manner favors M1 polarization through Nos2 transcription thereby inhibiting tumor growth, while spermine inhibits M1 but promotes M2 polarization, through enhancing autophagy by ATG5 upregulation." (PMID 39717382, 2024). "Interestingly, in our study, we found that hydrogen treatment actually alleviated ROS in CAFs and down‐regulated a key ROS‐induced gene, Nos2, and down‐stream pro‐tumor factors such as Mmp2, Cxcl1, and Cxcl12." (PMID 38757665, 2024). "NOS2 facilitates tumour cell angiogenesis, invasion, and metastasis through upregulating MMP9." (PMID 37795447, 2023). "However, NOS2 has also been proven to have both antitumoricidal functions and tumor suppressive properties in various tumors." (PMID 37346068, 2023). "In addition, IFNγ is necessary to stimulate tumor-specific NOS2/COX2 expression, which through a multifaceted process, also drives oncogenic pathways and shapes immunological profiles associated with poor prognosis." (PMID 37169743, 2023). "Increased inflammation at these NOS2 foci increases the likelihood of metastasis, and the discovery of the NOS2 positive niche at the tumor-stroma interface suggests that this may be the site of metastasis." (PMID 37169743, 2023). "Furthermore, we explored the expression pattern and the tumor suppressive role and mechanism of NOS2, which was one of the most significantly affected gene in our model." (PMID 37346068, 2023). "Therefore, we further investigated the effects of NOS2 on the tumor immune microenvironment (TIME) and metabolism in HB." (PMID 37795447, 2023). "Also, significant alterations in genes associated with tumor cell invasion were detected, such as significant upregulation of TGFβ1, ROAR, DAB2, BMP6, NOS2, PLXN2, and CADPS exhibited, and significant downregulation of TCF4." (PMID 38003292, 2023). "Given the predictive power of CD8+ T cell spatial localization, we observed abundant stroma-restricted CD8+ T cells with increased IFNγ expression in regions proximal to elevated tumor NOS2 expression, indicating a potential association between CD8+ T cells, IFNγ, and NOS2 regulation." (PMID 37169743, 2023). "This technique could be beneficial for describing tumor niches with increased aggressiveness that may respond to clinically available NOS2/COX2 inhibitors or immune-modulatory agents." (PMID 38187532, 2023). "Moreover, high NOS2-expressing tumor cells were proximal to areas with increased satellitosis, suggestive of cell clusters with a higher metastatic potential." (PMID 37169743, 2023).
tumor (continued). "NOS2 in immune mediators has anti-tumour and pro-inflammatory effects." (PMID 38136342, 2023). "And NOS2 is the only subtype that can achieve these NO levels over a period of time, indicating that NOS2 may play a role in both tumor-promoting and anti-tumor processes." (PMID 37958916, 2023). "Similar to the effect of exogenous NO, derived from myeloid cells or NOC-18, the rise in intracellular NO in Nos2-overexpressing cells suppressed T-cell expansion, which could explain the impaired tumor growth control in vivo." (PMID 36574610, 2023). "Tumor growth was significantly accelerated in a T cell–specific, Nos2-null mouse model." (PMID 36574610, 2023). "Together, these results suggest that NOS2 mainly functions as a tumor suppressor in CRC." (PMID 37346068, 2023). "This spatial analysis of the tumor microenvironment provides important insight into distinct neighborhoods where stroma-restricted CD8+ T cells exist proximal to NOS2-expressing tumor niches that could have increased metastatic potential." (PMID 37169743, 2023). "A decrease in the expression of NOS2 could indicate a more tumor-hostile environment and a potential clinical benefit." (PMID 37688629, 2023). "One example is that the sustained activation of type I IFN induces the upregulation of programmed cell death ligand 1 (PD-L1) in both tumor and dendritic cells and enhances the expression of nitric oxide synthase 2 (NOS2), leading to eventual resistance to PD-1 blockade." (PMID 37374093, 2023). "The product of the Nos2 gene (cluster 1, gene assigned to 11 terms related to infectious and neoplastic diseases), inducible NO synthase (iNOS), is a key enzyme for the synthesis of NO and a marker of the activity of the classical pro-inflammatory subpopulation of M1 macrophages." (PMID 36008994, 2022). "Additionally, we observed a decreased amount of nitric oxide synthase 2 in BBG-treated tumor mass in comparison to the control tumors." (PMID 34964926, 2022). "This reduction in intracellular cholesterol enhances IL-4 receptor (IL-4R)/STAT6/PI3K signaling in vitro and in vivo, promoting the expression of the typical M2 marker arginase-1 while inhibiting NOS2 and proinflammatory IL-12 expression, thereby promoting tumor progression." (PMID 34876704, 2022). "The difference of NOS2 positive expression rate between tumor tissues and normal tissues was statistically significant(χ2=17.261, P=0.000).ALOXE3 was positively expressed in 103 cases, with a positive expression rate of 72.5% (103/142), mainly showing moderate and strong positive expression." (PMID 35265525, 2022). "HIF1α promotes Th9 cell differentiation: (i) metabolically through TCA cycle metabolite, Succinate, and (ii) transcriptionally by transactivating Il9 and Nos2 gene loci, further enhancing Th9 cell polarization and Th9 cell-mediated anti-tumor effector functions." (PMID 34075041, 2021). "However, while a marker of immunosuppressive macrophages, MARCO engagement led to the expression of the pro-inflammatory genes Tnf, Il1b, and Nos2, leading to reduced primary tumor growth and metastases." (PMID 34572013, 2021). "Furthermore, NOS2/COX2 are linked to poor outcome and collaborate in feedforward loops in both cancer and immune cells in several tumor types, with ER- breast cancer being the best example." (PMID 34209132, 2021). "Loss of myeloid HIF-2α has been linked to decreased tumor inflammation and progression in murine models of breast and gastric cancer, while tumor-associated myeloid cells can also contribute to immune suppression by production of nitric oxide (NO), acting through the HIF-1α-NOS2 pathway." (PMID 34054802, 2021).
tumor (continued). "For instance, melanoma-derived exosomes promote the polarization of macrophages to an M1 (anti-tumoral profile) or M2 (pro-tumoral profile) phenotype, with increased upregulation of NOS2 and arginase, respectively, thereby suggesting a prooncogenic role for NO in the tumor microenvironment." (PMID 34200849, 2021). "Moreover, NOS2+CD68+ macrophages are enriched in tumor lesions from patients with colorectal cancer showing good response to neoadjuvant RT." (PMID 34079557, 2021). "It depends on the local concentration of NOS2 in the tumor microenvironment or disease state." (PMID 33374571, 2020). "Furthermore, we observed a positive correlation between distal colon weight (as surrogate of tumor burden) and the mRNA levels of TNFα, NOS2, and COX-2." (PMID 33489875, 2020). "Furthermore, G-CSFR−/− macrophages were characterized by higher levels of NOS2 expression and NO production, which led to greater tumor related cytotoxicity both in vitro and in vivo." (PMID 33036138, 2020). "In our experience, TME changed towards a more inflamed environment, evidenced by the increase of cytokines like CXCL10 and CCL2, and the decrease of immunosuppressive molecules (like FoxP3 and Nos2), and molecules that promote tumor growth and invasiveness (like IL10 and TGFβ)." (PMID 32064039, 2020). "Indeed, recent evidence suggests the ability of NOS2 to control hypoxic gradients within the tumor microenvironment (TME)." (PMID 33114647, 2020). "Upon TLR activation, M1 cells produce pro-inflammatory cytokines such as TNF-α, IL-12, and IL-6, which may promote tumor cell killing through NOS2 production and activation of T cells." (PMID 33036138, 2020). "Pairwise analysis showed significantly downregulated expression of ARG1 (by 2.2-fold, p = 0.025), DDAH1 (by 1.4-fold, p = 0.016), and DDAH2 (by 1.6-fold, p = 0.005) and upregulated expression of NOS2 (by 2.6-fold, p = 0.003) in tumor as compared to adjacent, macroscopically normal tissue." (PMID 32932854, 2020). "Moreover, targeting iNOS also had a positive effect on the immune cell content in the tumor environment, since NOS2 siRNA decreased the number of M2-type TAM in OVCAR-3 and Caov-3 xenografts." (PMID 30970628, 2019). "On the other hand, NOS2 inhibition could induce GSCs to release EVs with a modified cargo that is able to alter and manipulate the tumor inflammatory microenvironment in order to make it less advantageous to tumor growth and invasiveness." (PMID 31226744, 2019). "When analyzing major immune parameters in tumor-bearing mice between control and high salt fed mice, we could detect increases in Tnfa, Ifng, and Nos2 expression in spleen and tumor tissues, indicating a more pro-inflammatory environment in HSD mice." (PMID 31214164, 2019). "In addition, the CD45− fraction from MCA205WT tumors in vivo also expressed higher levels of Nos2 at later stages of PD-1 blockade with a trend towards higher NOS2 protein levels in mAb-treated tumor cells compared with isotype." (PMID 31481761, 2019). "Our observation showing that exacerbated NOS2 expression associated with tumor necrosis (data not shown) reinforces that interpretation." (PMID 31885577, 2019). "Expression of the classical M1 marker Nos2 was significantly decreased in tumors of IL27Rα KO mice, which may suggest a reduced anti-tumor potential of TAM in tumors of IL27Rα KO mice." (PMID 31637217, 2019). "Furthermore, PD-1 therapy further increases NOS2 expression which is regulated by type I (and type II) IFNs in both tumor cells and the tumor infiltrating myeloid fractions." (PMID 31481761, 2019). "Tumor cells upregulated Nos2 expression in response to type I or II IFN stimulation in vitro." (PMID 31481761, 2019). "Thus, the exosomes continuously released from metastatic LNs and additional exosome administration was enough to induce NOS2 expression in tumor-bearing mice." (PMID 29484119, 2018).
tumor (continued). "The ability of U-87 MG cells to generate neurospheres, which is a surrogate marker of GSC self-renewal, was also significantly affected by the presence of 1400W at 20 days of incubation, thus supporting the functional role of the NOS2/NO system in the sphere-forming ability of tumor stem cells." (PMID 30227679, 2018). "Tumour-derived mMDSCs showed higher levels of T-cell suppression in vitro that may be due to higher levels of nitric oxide synthase (NOS2) and arginase 1 (ARG1)." (PMID 28382931, 2017). "Moreover, according to the same Authors, the silencing of NOS2 expression by RNA interference decreased in vitro brain tumor initiating cells, highlighting the main role of NOS2 in tumor stem cell biology and maintenance." (PMID 28424427, 2017). "Additionally NOS2-expressing Tip-DCs are critical for tumor rejection in the context of ACT in mice." (PMID 28223985, 2017). "Together, these data suggest that mMDSCs may exert their effects on tumour cells via inducing NOS2 production." (PMID 28382931, 2017). "Interestingly, number of EMT/CSC-related factors such as IL1a, IL6, NOS2 and TGFb129, 35, 36, were highly expressed in BM or tumour-derived mMDSCs and also further enhanced the expression of these genes in tumour cells upon co-culture." (PMID 28382931, 2017). "In addition to number of inflammatory cytokines, NOS2 production in tumour cells was upregulated by mMDSCs." (PMID 28382931, 2017). "Interestingly, NOS2+ macrophages (M1) through NO production were found to be involved in T cell infiltration and tumor rejection." (PMID 29062041, 2017). "Likewise, nitric oxide-releasing aspirin (a typical aspirin linked to a nitric oxide donor) reduces arginase 1, NOS2, and PNT, while increasing the frequency and function of tumor-specific T cells, thus boosting the antitumor effect of cancer vaccination." (PMID 28223985, 2017). "Interestingly, it has recently been shown that synergic induction of COX-2 by IFN-γ and TNF-α limits type-1 immune response in tumor microenvironment by concomitant action of IL-10, NOS2, and Indoleamine 2,3-dioxygenase." (PMID 28018318, 2016). "Collectively, our data indicate that NOS2 drives the expansion of γδ T cells in pLNs at steady state, but may also support, at least in part, their accumulation within the tumor microenvironment." (PMID 27812136, 2016). "For example, the administration of beta-carotene increased theexpression of the NOS2 isoform, which could be detrimental in a model of tumor-bearingmice." (PMID 26200231, 2015). "The expression of Arg1 and Nos2 by tumor infiltrating immune cells was therefore evaluated by qPCR." (PMID 24982761, 2014). "Although poorly understood at present, a better understanding of how NOS2 expression influences the tumor environment may lead to the development of novel interventional strategies and improved clinical treatment." (PMID 25346730, 2014). "NOS2 has been involved in tumor growth, mutagenicity, angiogenesis and metastasis." (PMID 24316703, 2014). "NOS2 expression has proven be a useful marker for M1 macrophages in several tumor types." (PMID 25192022, 2014). "In a mouse model, studies on inflammation-related colon cancer demonstrated that the genetic deletion of NOS2 may lead to a reduction in tumorigenic capacity and that the inhibition of its activity may reduce the tumor load." (PMID 24024092, 2013). "To identify those Nos2-dependent effects promoting MB induction, we determined the features that were common to Ptch1+/+ Nos2−/− and Ptch1+/− Nos2−/− genotypes and persisted in the tumor tissues." (PMID 22438824, 2012). "Therefore, protein levels were particularly examined for differences between tumor samples from Ptch1+/− Nos2+/+ and Ptch1+/− Nos2−/− mice." (PMID 22438824, 2012).
tumor (continued). "For an initial assessment of the molecular tumor characteristics, gene expression of hedgehog signaling pathway components were measured in 21 MBs and 24 normal (adult) cerebellar tissue samples from both Ptch1+/− Nos2+/+ and Ptch1+/− Nos2−/− mice." (PMID 22438824, 2012). "Once stabilized, HIF-1α translocates into the nucleus, dimerizes with HIF-1β, and activates the transcription of target genes such as Vascular Endothelial Growth Factor (VEGF) and Nitric Oxide Synthase 2 (NOS2), which are highly related to tumor growth and survival." (PMID 23166763, 2012). "The inducible enzymes COX2 and NOS2 were up-regulated in both tumor and peritumor tissue." (PMID 21489226, 2011). "Therefore, the spatial localization of NOS2 expressing tumor cells relative to CD8+ T cells could be key determinants of clinical outcomes." (PMID 39356141, 2024). "In this study, we observed that hydrogen treatment could alleviate intracellular reactive oxygen species (ROS) of CAFs, disturb the transcriptional program through down‐regulating nitric oxide synthase (Nos2) expression level, and reverse CAFs’ tumor‐promoting and immune suppressive phenotypes." (PMID 38757665, 2024). "Significantly, barring one tumor from deceased and two tumors from alive patients, deceased patient tumors had mixed NOS2 and CD8+ T cell levels, which could be separated into both NOS2 and CD8 low immune desert regions and NOS2 high, stroma-restricted CD8+ T-cell inflamed regions." (PMID 39356141, 2024). "Given that the flux of NOS2-derived NO depends on the local density of NO producing cells as well as the concentration, diffusion, and reaction kinetics, we used density heat map analyses to assess tumor NOS2 and COX2 clustering in tumors from deceased versus alive patients." (PMID 39356141, 2024). "Therefore, the expression of Il6, Nos2, Ccl2, Spp1, Tnf, Acat2, Aox1, Crem, Gls2, Per3, Pink1, Txnip, and Ypel3 was examined in acidosis upon simultaneous transfection with microRNA mimics or antagomirs in two tumor lines in vitro and in vivo." (PMID 38069241, 2023). "Taken together, these data suggest that NOS2 might have a tumor suppressive function in CRC." (PMID 37346068, 2023). "Moreover, neutrophils upregulated the expression of Nos2, which could contribute to their tumor-suppressive activity." (PMID 37554264, 2023). "The gene markers of M1 macrophages, such as PTGS2 and NOS2, had weak correlations with CD209 expression, whereas M2 macrophage markers had moderate and strong correlations, revealing the potential regulatory role of CD209 in tumor-associated macrophage (TAM) polarization." (PMID 35783255, 2022). "As NOS2 overexpression has been associated with transformed epithelial cells and that of ARG and ODC with tumor-infiltrating macrophages, possible low content of these immune cells in tumors analyzed in the present study might account for lack of ARG and ODC upregulation." (PMID 34439753, 2021). "After adjusting for tumor purity, the results showed that ATF3 expression was significantly correlated with macrophage subpopulations, including tumor-associated macrophages (TAMs; CCL2, r = 0.245, P = 4.16e−06), M1 (NOS2, r = 0.137, P = 0.08e−02), and M2 (CD163, r = 0.141, P = 8.90e−03)." (PMID 33407456, 2021). "At both time points, FAK inactivation within fibroblasts significantly decreases the pro‐tumoural M2 macrophage number (CD206+ tumour‐associated macrophages), while not affecting the total macrophage number, but increasing the M1 (Nos2+) macrophage number only in early setting." (PMID 33025708, 2020). "However, at the protein level, flow cytometry analyses performed after 4 injections of mAb revealed two-fold higher NOS2 expression in CD11c+ as well as F4/80+/Gr1− fractions of CD45+ tumor infiltrating cells from anti-PD-1-treated mice compared with isotype-treated controls." (PMID 31481761, 2019).